CABCOCO1 (ciliary associated calcium binding coiled-coil 1)
Description:
Calcium-binding protein. May be involved in the control of sperm flagellar movement.
Synonyms: C10orf107; bA63A2.1; Em:AC022398.2; MGC44593; ARIEL
Tractability: No criterion of Open Targets' tractability assessment is met for any kind of drug.
Gene: Protein-coding gene on chromosome 10 (61,662,929 to 61,766,845, forward strand). Ensembl gene ENSG00000183346.
Subcellular location: Cytoplasm; Cytoplasm, cytoskeleton, microtubule organizing center, centrosome; Cell projection, cilium, flagellum
Subcellular location (Human Protein Atlas): Basal body; Centrosome; Cytosol; Nucleoplasm
Gene Ontology:
Molecular function: protein binding; calcium ion binding
Cellular component: centrosome; cytoplasm; sperm flagellum; motile cilium
Genetic constraint (gnomAD): Loss-of-function variants: 10 observed, 14.75 expected, observed/expected ratio (o/e) 0.68, 90% interval 0.42 to 1.15. The upper end of that interval is the gene's LOEUF score, 1.15, which puts it in group 5 of 6, group 1 being the genes least tolerant of losing a copy. Missense variants: 142 observed, 153.35 expected, observed/expected ratio (o/e) 0.93, 90% interval 0.81 to 1.06. Synonymous variants: 46 observed, 49.83 expected, observed/expected ratio (o/e) 0.92, 90% interval 0.73 to 1.18.
Homologues: Orthologues: macaque CABCOCO1 (93% identical), dog CABCOCO1 (82% identical), pig CABCOCO1 (82% identical), rabbit CABCOCO1 (81% identical), guinea pig CABCOCO1 (75% identical), rat Cabcoco1 (69% identical), chimpanzee CABCOCO1 (69% identical), mouse Cabcoco1 (69% identical), tropical clawed frog cabcoco1 (32% identical), zebrafish cabcoco1 (29% identical).
Diseases named in the same sentence as CABCOCO1 in open-access papers:
CABCOCO1 is named in the same sentence as 6 diseases in open-access papers, as found by Europe PMC text mining. Sharing a sentence is not in itself a finding about the gene and the disease.
CABCOCO1 shares sentences with these, for which no sentence is quoted: cancer (3 papers); acute myeloid leukemia (1); COVID-19 (1); glioma (1); Hypertension (1); osteosarcoma (1).